S100A11 (S100 calcium binding protein A11)
Diseases named in the same sentence as S100A11 in open-access papers (continued):
Sharing a sentence is not in itself a finding about the gene and the disease.
tumor (continued). "In brief, our study showed that S100A11 could be used as a potential carcinogen and prognostic marker for most tumor types." (PMID 36605485, 2023). "In addition to cell proliferation, migration and invasion are also of crucial importance for cancer metastasis 26, 28, so we performed Transwell migration and invasion assay to detect the role of S100A11 in tumor metastasis." (PMID 36860671, 2023). "However, LKO mice treated with SAM or depleted S100a11 showed a significant reduction in tumor volume and number as well as lung metastatic nodules compared with those of untreated LKO mice." (PMID 37166978, 2023). "Furthermore, the dysregulated expression and cancer-promoting effect of S100A11 have been reported in certain tumor tissues." (PMID 36605485, 2023). "However, the biological function of S100A11 in the tumor microenvironment (TME) has been rarely reported." (PMID 36605485, 2023). "However, a correlation was found between the transcript levels of S100A13 and S100A11 (R = 0.67), in the tumor array." (PMID 37627239, 2023). "Interestingly, S100A11 has also been discovered as a tumor-derived EVP protein implicated in eliciting immunological responses, suggesting that it is important in tumor immunity." (PMID 35510040, 2022). "On the other hand, in bladder cancer, S100A11 is thought to function as a tumor suppressor." (PMID 34179021, 2021). "In most cancers, S100A11 is highly expressed and correlated to tumor promotion and progression." (PMID 34179021, 2021). "Studies have found that in renal cell carcinoma, which is prevalent in North America, the expression level of S100A11 is positively correlated to the degree of cancer progression and tumor size, and negatively correlated to the disease-free survival rate of patients." (PMID 34179021, 2021). "Up-regulation of CASP4 and S100A11 may contribute to the inflammatory status in the tumor immune microenvironment for the proliferation, differentiation and survival of tumor cells." (PMID 35118063, 2021). "Additionally, S100A11 protein level tends to be increased in advanced stages of GC or deeper tumour infiltration." (PMID 33931048, 2021). "Apart from confirming targets, such as ERBB2 and S100A11, which are exclusively upregulated in the tumour epithelial cells, qPCR data confirmed that stromal targets such as SPARC, TIMP1, IGFBP7, COL1A1 were upregulated specifically in stromal components and not in epithelial components." (PMID 31959771, 2020). "In vivo imaging system revealed that significant differences in the tumour volume between U87 cells transfected with sh‐S100A11 and with its control, mice bearing U87 cells transfected with sh‐S100A11 displayed a significant reduction compared with xenografts transfected with shCtrl." (PMID 31430050, 2019). "We also demonstrated the S100A11 on tumour growth in GBM using an orthotopic tumour xenografting." (PMID 31430050, 2019). "In addition, tumour cell pseudopod-specific proteins (AHNAK, Septin-9, eIF4E, and S100A11) were identified from the transcriptome/proteome analysis and closely for pseudopod formation, actin cytoskeleton dynamics, and tumour cell migration and invasion." (PMID 30504808, 2018). "S100A11 has a number of contrasting roles in the regulation of tumor growth." (PMID 25780452, 2015). "Based on a tissue array containing 21 tumor types, the localization of S100A11 was shown to change from strictly nuclear in normal tissues to cytoplasmic and nuclear in many common cancers, which may contribute to enhanced proliferation of cancer cells." (PMID 25940438, 2015). "In addition, overexpression of cPLA2 protein was observed in 64% of the NSCLC tumor species overexpressing S100A11 protein, compared to corresponding normal tissues." (PMID 25940438, 2015).
tumor (continued). "In summary, S100A11 knockdown and TLR3 overexpression promoted anoikis and diminished the malignancy of tumor cells, indicating that S100A11 expression might be positively correlated with anoikis resistance and a poor prognosis, whereas TLR3 expression was negatively correlated." (PMID 39981252, 2025). "Moreover, exosomal S100A11 activated IFITM3/Akt passway in tumour cells." (PMID 39756316, 2024). "We further ascertained whether PCK1-induced tumor suppression could be rescued by S100A11." (PMID 37166978, 2023). "S100A11 could promote proliferation, migration, and invasion of tumor cells in multiple cancers." (PMID 35646893, 2022). "Therefore, conversely, one of the reasons for the invasivity of this type of tumor may be that S100A11 induces phosphorylation of SMAD2/3 through TGF-β, which then accelerates the process of tumor cell migration, tissue infiltration, and EMT." (PMID 34179021, 2021). "Moreover, high S100A11 mRNA expression correlated with advanced tumor stage and poor prognosis." (PMID 33815482, 2021). "Thus, under these conditions, S100A11 acts as a tumour‐suppressor factor." (PMID 31430050, 2019). "Dual staining for S100-A11 and α-SMA further supported the presence of S100-A11-expressing CAFs in patient tumours." (PMID 42155177, 2026). "Knockdown of S100A11 significantly suppressed CRC cell proliferation, induced apoptosis, and restrained tumor development in a xenograft model." (PMID 40567612, 2025). "In prostate cancer, Han and colleagues found that Erdafitinib treatment combined with S100A11 knockdown in PCa cells and CAFs increased infiltration of effective CD8+ T cells in the tumor, thereby reducing tumorigenicity." (PMID 40427733, 2025). "Earlier studies have shown that SAM exert a potent anti-tumor effect in mouse models of HCC by acting as a methyl donor to modify H3K9me3 and inhibiting the oncogene S100A11." (PMID 40019515, 2025). "Knocking down S100A11 only in tumor cells decreased a subset of CAFs and increased CD4+ T cells, but improvements in tumor volume and CD8+ infiltration were limited." (PMID 41514658, 2025). "Based on both the DEN/DEN-HFD and the LPTENKO models, we identified a crucial protective role for S100A10 on tumoral initiation, in MASLD setting, whereas S100A11 favors growth of tumors in two out of 3 models analyzed." (PMID 40841353, 2025). "Another gene set was the S100 family including S100A11, S100P and S100A6, which mediate tumor progression and metastasis through their roles in cell motility, invasion, and angiogenesis." (PMID 40018643, 2025). "Functionally, S100A11 knockdown in CRC cell lines inhibited cell proliferation, invasion, and migration, leading to decreased tumour growth and metastasis in vivo." (PMID 40374593, 2025). "Studies also noted that the dysregulation of S100A11/ANXA2, one node of a tumour suppressor/oncogene network, was found in the early stage of steatosis and was involved in the development of inflammation and liver cancer." (PMID 39756316, 2024). "S100A11 is reported to interact with miR-22 in MG63 OS cells, and it suppresses the anti-tumor action of miR-22." (PMID 36943734, 2023). "S100A2, S100A11, and S100A14 are three S100s with complex roles in cancer, as they have been described as either tumor suppressors or tumor promoters." (PMID 37627239, 2023). "Collectively, these results support the finding that PCK1 deficiency alleviates SAM biosynthesis and H3K9me3 modification in S100A11, thereby promoting aberrant PI3K/AKT activation and tumor progression in human primary HCC." (PMID 37166978, 2023). "Conversely, S100A11, p-AKT, MMP11, and N-cadherin expression was higher in tumor tissues than in adjacent normal tissues." (PMID 37166978, 2023). "Despite extremely high tumor heterogeneity, malignant cell markers such as MUC1, CEACAM5, S100A11, CD24, and TM4SF1 were relatively uniformly upregulated in cancer cells and had the potential to serve as targets for SBA diagnosis and treatment." (PMID 36104333, 2022).
tumor (continued). "In our study, 90 tumour tissues of PDAC and 60 paired paracancerous tissues were used to assess S100A11 protein expression using TMA." (PMID 35752610, 2022). "Compared with para-cancer tissues, the expression levels of S100A4/S100A6/S100A10/S100A11/S100A13/S100A14/S100P were higher in HCC tissues, while the expression levels of S100A8/S100A9/S100A12 were decreased in tumor tissues." (PMID 33815482, 2021). "It has been reported that high expression of the S100A11 gene in some tumors can upregulate the expression of MMP-9, thus promoting tumor invasion." (PMID 33763485, 2021). "It showed that the high intensity (2 and 3) of the S100A11 staining occurred more frequently in malignant and metastatic (MET) tumour tissues than in the normal adjacent (NAT) and normal stomach tissues." (PMID 33931048, 2021). "PD-L1 expression positively correlated with high expression levels of tumor promoting genes such as CD68, ADAM12, FXYD5, S100A11, CD46, and MED19 (and ST1D)." (PMID 33415077, 2020). "In this study, we found that extracellular S100A11, via RAGE, has a critical role in tumor progression of MPM." (PMID 29362358, 2018). "S100A11 targeted to the nucleus and/or cytoplasm activated Smad pathway and induced EMT, which is very similar to tumor-promoting properties of the upstream stimulatory factors LASP1 or TGFβ." (PMID 27181092, 2016). "Positive rate of cytoplasmic and nuclear S100A11 expression was significantly higher in CRC tissues, compared to adjacent non-tumor samples (P < 0.05)." (PMID 27181092, 2016). "As shown in, S100A11 was up-regulated in CRC samples, compared to adjacent non-tumor tissues (P = 0.0228)." (PMID 27181092, 2016). "The roles and mechanisms of key genes in Anoscore, such as S100A11 and TLR3, in biological functions, including anoikis, tumor progression, immune modulation and drug sensitivity, warrant further comprehensive investigation through in vitro and in vivo experiments." (PMID 39981252, 2025). "Tumor number incidence and size was monitored in LPTENKO mice with hepatocyte-specific knock-down of S100A10 or S100A11 through in vivo MRI imaging every month, in order to investigate the effect of S100A10/S100A11 downregulation on hepatic carcinogenesis in a MASLD context." (PMID 40841353, 2025). "Functional characterization revealed that S100A11, a key exosomal biomarker, promotes CRC progression in vitro by enhancing proliferation, and anti-apoptotic signaling, while its in vivo knockdown suppressed tumor growth, underscoring its oncogenic potency." (PMID 40567612, 2025). "Additionally, S100A11 interacts with the receptor for advanced glycation end products (RAGE), contributing to the inflammatory tumour microenvironment and resistance to apoptosis." (PMID 40374593, 2025). "Additionally, S100A11 and S100A4, as calcium-binding proteins, have been reported to promote tumor metastasis by activating inflammatory pathways such as NF-κB." (PMID 40740857, 2025). "Because S100A9 and S100A11 showed a strong involvement in the aggressiveness of GBM and could have a direct effect on RAGE, the effect of Azeliragon on GBM tumor tissue was examined." (PMID 39744679, 2025). "And then S100A11 bound to IFITM3 and exerted the pro-tumour effect by activating Akt pathway." (PMID 39756316, 2024). "Moreover, S100A11 binds to IFITM3, inducing Akt phosphorylation of living tumour cells after chemotherapy, which promotes tumour progression." (PMID 39756316, 2024). "However, in the tumor array, positive correlations were observed between S100A14 and S100A2 (R = 0.50), S100A4 (R = 0.55), S100A6 (R = 0.45), S100A7 (R = 0.47), S100A11 (R = 0.65), S100A16 (R = 0.57) and S100P (R = 0.66)." (PMID 37627239, 2023). "However, correlations were observed between S100A2 and S100A7 (R = 0.48), S100A11 (R = 0.54), S100A14 (R = 0.50), S10016 (R = 0.61) and S100P (R = 0.85), when comparing transcript levels from the tumor array." (PMID 37627239, 2023).
tumor (continued). "However, some members of the S100 family have been reported to be tumor suppressors, including S100A2, S100A11, and S100A9." (PMID 35760899, 2022). "Remarkably, upon the inoculation of a lower number of cells (5 × 104 SW1990 and 2 × 104 BxPC3), S100A11-knockdown cells did not form tumours, while untreated cells formed tumours in some cases." (PMID 35752610, 2022). "Proteins that were perturbed in expression level in the peripheral or in the central part of the tumor as compared with the non-involved part included S100A11, HNRNPF, HNRNPH1 or HNRNPH2, GSTP1, PKM and FABP1." (PMID 34563043, 2021). "Moreover, SRGN, S100A11, and FCER1G contribute to the identification of mast cells in tumor microenvironments." (PMID 34575089, 2021). "Significant differential expression was observed by 2D-PAGE for S100A11 identified from spot 5006 in the central part of the tumor compared with the non-involved part." (PMID 34563043, 2021). "Immunohistochemical S100A11 expression is significantly correlated with the nodal status, but not tumor depth or grading." (PMID 23166536, 2012). "CNV score analysis revealed that Malignant, CASC15+KLK6+EPC, and UBD+S100A11+EPC exhibited significantly higher CNV scores than other subpopulations, indicating that these cells have a higher malignant potential and may play a key role in tumor progression." (PMID 40932351, 2026). "We also conducted co-culture-based transwell migration assays and observed that the migratory ability of M0/M1/M2 macrophages was unaffected by S100A11 knockdown, indicating that cluster C6 cancer cells might not likely recruit TAMs to the tumor site." (PMID 38169544, 2024). "Together with the tumor-suppressing proteins such as CALR, ENO1, HSP, MSN, and UBC, which were enriched in tumor-suppressive CM, six recombinant proteins, such as HISTONE H4, PPIB, GJA1, CPE, S100A11, and PCOLCE, were identified as extracellular tumor-suppressing proteins." (PMID 36943734, 2023). "However, the role of S100A11 protein in tumour cell response to chemotherapeutic drugs has not been characterised." (PMID 33931048, 2021). "Unfortunately, multivariate analysis showed that tumor differentiation, N classification and M classification, but not S100A11 expression, had positive predictive values for overall survival, implying the failure to identify overexpression of S100A11 as an independent prognostic factor." (PMID 27181092, 2016). "Moreover, correlation analysis revealed that PCK1 protein abundance was positively correlated with H3K9me3 in HCC tumor samples (r = 0.4092, P = 0.0035), while negative correlations were observed between S100A11 and H3K9me3 (r = –0.4235, P = 0.0024) and PCK1 (r = –0.5169, P = 0.0001)." (PMID 37166978, 2023). "In light of this, we found that S100A11 silencing resolved MASLD development in a chronic stage, and slowed down tumor growth without affecting the number of nodules." (PMID 40841353, 2025). "Finally, regarding S100A11, on which the effect of curcumin has never been investigated so far, the first studies on its implication in EMT in cancer revealed this protein was present in a list of 19 pseudopod-specific proteins common to six metastatic human tumor cell lines." (PMID 35873564, 2022). "However, targeting S100A11 downregulation to attenuate liver tumor incidence, although potentially promising approach, it also leads to the downregulation of the hepatoprotective S100A10, which might explain the absence of beneficial outcome on tumor incidence." (PMID 40841353, 2025).
cancer (94 papers, 2004 to 2026). A tumor composed of atypical neoplastic, often pleomorphic cells that invade other tissues. "S100A11 regulated the TME by modulating interactions between cancer-associated fibroblasts (CAFs) and M2 macrophages." (PMID 41668902, 2026). "Consistent with reports in other cancers, S100A11 is upregulated in CRC and is associated with poor survival outcomes." (PMID 40374593, 2025). "Meanwhile, existing studies also suggest that S100A11 has the potential to be a potential carcinogen and prognostic marker associated with the pan-cancer immunosuppressive microenvironment." (PMID 39854580, 2025). "As S100A11 is significantly associated with high pathological stages in distinct cancer entities, deregulated S100A11 should be considered as an oncogenic factor." (PMID 38408765, 2024). "Compiling evidence has indicated that S100A11 expression at high levels is closely associated with various cancer species." (PMID 38842658, 2024). "In summary, our study proved that elevated S100A11 expression was associated with the immunosuppressive TME in pan-cancer." (PMID 36605485, 2023). "A previous study reported that overexpression of S100A11 is associated with the metastasis of cancer." (PMID 25780452, 2015). "S100A11 has been found to be linked to the prognosis of a number of cancers in various studies." (PMID 38129538, 2023). "Indeed, in other types of cancer such as melanoma, lung, ovarian and pancreatic carcinomas, S100A11 levels were found to be increased and linked with bad prognosis." (PMID 36232334, 2022). "The dysregulation of S100A11 is linked with oncogenic activities including cancer progression." (PMID 33931048, 2021). "The overexpression of S100A11 is also associated with cancer progression and poor survival." (PMID 33134167, 2020). "In cancer cells decreased levels of S100a11 have been associated with invasive forms." (PMID 31355153, 2019). "CLU, NDRG1, CD166, S100A11 and Galectin-1 were associated with carcinoma and Galectin-3." (PMID 28701735, 2017). "The authors hypothesized that in normal breast S100A11 translocates to the nucleus which increases transcription of negative regulators of cell growth, while in cancer the loss of nuclear translocation may lead to an inability to control cell growth." (PMID 22727333, 2012). "Among the predicted targets in the StarBase database, the gene S100A11 was noted for its elevated expression across various cancer tissues." (PMID 39879906, 2025). "Research indicate that CRC overexpresses S100A11, and S100A11 undergoes nucleocytoplasmic translocation during cancer development, potentially impacting cancer cell proliferation." (PMID 40240912, 2025). "Through correlation analysis, we observed that LAD1 expression levels were statistically associated with several cancer-related genes, including SFTPB, S100A6, CEACAM6, KRT19, S100A10, ANXA2, S100A11, and CAPN2." (PMID 41423496, 2025). "S100A11 plays a crucial role in diseases, including cancers, metabolic diseases, and inflammatory diseases." (PMID 39791167, 2025). "New evidence suggests that S100A11 is highly expressed in many cancers, and is closely related to malignant proliferation, distant metastasis and a poor prognosis." (PMID 39981252, 2025). "The present work shows that silencing S100A10 or S100A11 resulted in distinct outcomes in hepatic malignant transformation and cancer progression." (PMID 40841353, 2025). "The role of S100A11 in promoting cell proliferation and inhibiting senescence, as demonstrated in our study, provides a mechanistic insight into its contribution to cancer pathology." (PMID 40374593, 2025). "Taken together, this study provided insights on the presence of a cancer-stemness subpopulation of HCC cells with S100A11 as its downstream mediator." (PMID 38169544, 2024).